TNF (tumor necrosis factor)
Diseases named in the same sentence as TNF in open-access papers (continued):
Sharing a sentence is not in itself a finding about the gene and the disease.
cancer (continued). "Cancer-related systemic inflammation activates pro-inflammatory cytokines, including interleukin (IL)-1, IL-6, and tumor necrosis factor alpha, which suppress appetite by acting on the hypothalamus and contribute to catabolic processes, including muscle degradation and lipolysis." (PMID 40627291, 2025). "Interestingly, through exogenous administration, TNF can also play a dual role in anti-cancer therapy." (PMID 40170120, 2025). "However, it is worth noting that among UC patients who developed cancer, only two (11%) were under anti-TNF alpha therapy at the time of cancer diagnosis." (PMID 40361323, 2025). "Notably, TNF-α-induced phosphorylation of RelA at serine 276 in certain cancer cells facilitates the recruitment of DNA methyltransferase 1 (Dnmt1) to tumor suppressor genes (e.g., BRMS1)." (PMID 40562870, 2025). "The transition from inflammation to cancer may be mediated by several regulatory molecules, including chemokines, proinflammatory cytokines, TNF, and IL-6, which are crucial in promoting the growth, proliferation, and invasion of cancer cells." (PMID 40051564, 2025). "However, evidence directly assessing the relationship between TNF inhibitor therapy and cancer in AS remains limited." (PMID 41302997, 2025). "In addition, the researchers designed a surface-enhanced Raman scattering (SERS) assay based on DNA origami plasma nano-antennas for monitoring cytokines relevant to cancer immunotherapy, such as tumor necrosis factor-α (TNF-α) and IFN-γ." (PMID 40585578, 2025). "This is the first study to prospectively evaluate the clinical value of novel biomarkers (IL-6, MPO, TNF-alpha) in cancer patients as potential biomarkers of cancer therapy-related cardiac dysfunction, defined according to current ESC cardio-oncology guidelines." (PMID 40362309, 2025). "Finally, the pro-inflammatory cytokine TNF is also responsible for significantly promoting cancer progression by facilitating cellular invasion and metastasis." (PMID 40733296, 2025). "For instance, stimulation of muscarinic type 1 receptors in murine PDAC models has been shown to suppress the cancer stem cell compartment, reduce CD11b+ myeloid cell infiltration, lower tumor necrosis factor α (TNF-α) levels, and inhibit metastatic growth in the liver." (PMID 40149585, 2025). "Meanwhile, chronic inflammation in adipose tissues increases the secretion of cytokines including IL-6 and TNF, which may contribute to cancer development." (PMID 40535346, 2025). "A Swedish nationwide study documented modest excess cancer cases with anti-TNF therapy (2.7 per 1000 person-years; HR = 1.41, 95% CI 1.24–1.62), primarily due to colorectal and hepatobiliary cancers, likely reflecting more aggressive disease rather than therapy." (PMID 41228267, 2025). "Finally, KEGG pathway analysis further supported involvement in immune-related and oncogenic signaling, including the cytokine–cytokine receptor interaction, TNF signaling pathway, NF-kappa B signaling pathway, apoptosis, and broader pathways in cancer." (PMID 41463479, 2025). "CD8+ cells in particular are among the most powerful immune cells and serve as a central focus of successful cancer immunotherapies, these cells can kill cancer cells directly by releasing cytotoxic factors such as granulozyme and tumor necrosis factor-α (TNF-α)." (PMID 40547025, 2025). "Cardamonin has also been reported to inhibit TNF-α-induced NF-κB activation in cancer cells." (PMID 41302385, 2025). "PA induces anti-inflammatory effects on IL-6 that may reduce the activity of pro-inflammatory cytokines IL-1B and TNF-a, positively affecting cancer-related fatigue." (PMID 39915872, 2025). "Moreover, Hallmark gene set for cancer‐related pathways (e.g., EMT, IL6 and TNFα signals) were exclusively enriched in ALB+KRT7+ EPCs from AC samples." (PMID 39834100, 2025).
cancer (continued). "Published data have not shown an increased risk of new cancer with TNF inhibitors compared with conventional synthetic DMARDs (csDMARD) in patients with a history of solid cancer." (PMID 40282506, 2025). "When all three cannabinoids were used simultaneously, the greatest decrease in TNF-α level was detected (20.80 ± 4.64), suggesting that their effects may be synergistic when used to control inflammation related to cancer formation." (PMID 40008130, 2025). "The downregulation of AQP4 may increase TNF-α expression in the gastric mucosa by activating the NF-κB pathway, further exacerbating inflammation and promoting cancer cell proliferation and migration." (PMID 40255569, 2025). "Altogether, these findings demonstrate that DHC has cytostatic properties against cancer cells, especially in the presence of TNF-α, by inducing cell cycle arrest in the G1 phase correlated with the downregulation of cyclin D1 expression and RB protein phosphorylation." (PMID 40507823, 2025). "GSEA further linked high EOGT expression to the activation of pro-cancer pathways, including EMT, angiogenesis, inflammatory response, and TNFα signaling via NFκB, while suppressing oxidative phosphorylation, suggesting EOGT’s involvement in multiple oncogenic pathways." (PMID 40299340, 2025). "These modifications involve expressing immunostimulatory heterologous genes, such as interleukin-12 (IL-12), granulocyte/macrophage colony-stimulating factor (GM-CSF), interferon-gamma (IFN-γ), interleukin-2 (IL-2), or tumor necrosis factor-alpha (TNF-α) in various human cancers." (PMID 40722781, 2025). "Mechanism and clinical significance of IL - 6, TNF-α and IL - 1β in cancer progression." (PMID 41000397, 2025). "This dual role underscores the importance of the TNF-α–NF-κB axis in balancing immune responses, tissue repair, and cellular fate, all of which are central to both immune defense and disease pathogenesis, including cancer." (PMID 40558596, 2025). "Among the various CD4+ T cell subtypes that regulate immune responses, the CD4+ T helper 1 (Th1) subset, which produces interferon (IFN)γ, tumor necrosis factor alpha (TNF-α), and interleukin-2 (IL-2), plays a central antitumor role by orchestrating cell-mediated immunity against cancer." (PMID 40543509, 2025). "In addition, msbB-deficient ST strains have been investigated in cancer immunotherapy, where they tend to induce a Th2-skewed immune response, characterized by reduced IFN-γ and TNF-α production." (PMID 41304196, 2025). "Additionally, cancer‐related inflammation, characterized by elevated cytokines such as TNF‐α and IL‐6, further disrupts insulin signaling, exacerbating metabolic dysfunction." (PMID 40195579, 2025). "While long-term studies do not suggest a significant rise in cancer risk among bDMARD users, data on TNF inhibitors remain inconclusive." (PMID 40142915, 2025). "TNF-α is a pro-inflammatory cytokine that plays a multifaceted role in cancer prognosis." (PMID 41432145, 2025). "Patients with a history of malignancy may also opt for abatacept over TNF inhibitors, as they have demonstrated a more favorable safety profile in this regard." (PMID 40142915, 2025). "Despite a comparable mean age, the incidence observed in our TNF inhibitor-treated cohort was lower, suggesting that TNF inhibitor therapy does not confer an excess cancer risk." (PMID 41302997, 2025). "In addition, co-administration of pablizumab (an PD-1 inhibitor) with CAR-T cells has also been found to restore the production of interferon-gamma (IFN-γ) and tumor necrosis factor-alpha (TNF-α) which can further facilitate anti-cancer immunity." (PMID 41024300, 2025). "Moreover, TNF-α enhances the invasive characteristics of cancer cells through the induction of EMT, which is mediated by mechanisms dependent on Snail or ZEB1/ZEB2." (PMID 39941858, 2025).
cancer (continued). "CD4+ Th cells assist in activating CD8+ CTLs and also produce cytokines that indirectly contribute to the anti-cancer immune response, common pro-inflammatory cytokines include IL-1, IL-6, IL-8, and tumor necrosis factor-α (TNF-α), while common anti-inflammatory cytokines include IL-4 and IL-10." (PMID 40881864, 2025). "As with the other immunosuppression-related tumors, anti-TNF may in fact reduce the activity of the immune system in inhibiting cancer cells in the brain." (PMID 41008635, 2025). "The mean age of patients at TNF inhibitor initiation was 39.2 ± 13.0 years; 75.9% were male, 90.1% were HLA-B27-positive, approximately half were ever smokers, and 2.8% had a history of cancer." (PMID 41302997, 2025). "Another key cytokine involved in both aging and cancer is TNF-α." (PMID 41294748, 2025). "Next, we grouped them into cytokines associated with pre-cancer or the initiation stage of HCC (IL-6, TGF-β, MCP-1, FGF2, IL-2, IL-8, IL-12p40, IL-12p70, IL-18, IP-10, TNF-α, and IFN-γ), the early stage of HCC (OPN, GDF-15, RANTES, and VEGFA), and the advanced stage of HCC (IL-10, and MIP-3)." (PMID 41219858, 2025). "Notably, our observation that high TNF-α accompanies advanced disease aligns with studies in other cancers." (PMID 40299527, 2025). "During acute inflammation, elevated levels of tumor necrosis factor-α, interleukin-1, and interleukin-6 may induce abnormal cell proliferation and malignant tumor progression." (PMID 40272695, 2025). "In summary, FUBP3 regulates the expression of numerous genes involved in cancer regulation, as well as genes pertinent to T cell activation, cell cycle processes, and TNF-α-induced inflammation via the NF-κB pathway in J-Lat 10.6, uninfected Jurkat, and uninfected primary CD4+T cells." (PMID 40248217, 2025). "The role of TGF‐β, TNF‐α, IL‐10, IL‐6, and chemokines is more complex, as they may promote or inhibit cancer in a context‐dependent manner." (PMID 40356340, 2025). "At the same time, an abundance of inflammatory cytokines and cytokine receptors in the common target may be engaged in the cancer pathway, including TNF, IL6, and IL2." (PMID 39492771, 2025). "Addressing this question could improve our understanding of TNF's complex and seemingly paradoxical roles in cancer progression and may serve as a foundation for developing more targeted immunotherapies." (PMID 40977146, 2025). "Moreover, both Meclofenamate and Tonabersat have been found to lower the release of IFN-α and TNF-α in astrocyte cancer cell co-cultures." (PMID 39858080, 2025). "Additionally, osteocyte-secreted tumor necrosis factor-alpha (TNF-α) suppresses cancer proliferation, though this effect is antagonized by tumor-derived transforming growth factor-beta (TGF-β)." (PMID 40735673, 2025). "In addition, CTL also can induce cytotoxic effects on cancer cells by secreting interferon-γ and tumor necrosis factor α." (PMID 39931056, 2025). "The CD8+ CTLs could promote their anticancer effects by releasing IFN-γ and TNF-α, which trigger cytotoxic responses in cancer cells." (PMID 39744497, 2025). "Our results preliminary revealed that milk exosomes might increase the level of TNF-α, IFN-γ, and IL-12 in vivo, which was closely associated with the innate immune response against cancer cells." (PMID 39744423, 2025). "Interestingly, well-established pro-tumorigenic pathways commonly associated with cancer, such as hypoxia signaling, epithelial-to-mesenchymal transition (EMT), and tumor necrosis factor alpha (TNF-α) signaling, were found to be suppressed." (PMID 41333208, 2025). "TNF- mRNA expression has been only seen in the four instances’ most aggressive cancer cells." (PMID 41476448, 2025).
cancer (continued). "By inhibiting NF-kB activation, SsnB may diminish the expression of its target cytokines, including TNF-α, IL-1β, and IL-6, which are critical for maintaining cancer cell viability and immune evasion." (PMID 40143078, 2025). "KEGG pathway enrichment analysis identified up- and down-regulated inflammatory response pathways and significant enrichment in metabolic pathways, as well as in pathways related to cancer, immune response, and inflammation, including the TNF signaling and NF-κB signaling pathways." (PMID 40384854, 2025). "This aligns with findings from a network meta-analysis in cancer patients showing that combined aerobic and resistance training was superior to single-modality exercise in reducing inflammatory markers such as IL-6, IL-8, IL-10, TNF-α, and CRP." (PMID 41583457, 2025). "Additionally, these extracts and their active compounds demonstrate cancer prevention properties by inhibiting the production of IL-2, TNF-α, and NO." (PMID 40022126, 2025). "In cancer and carcinogenesis, dysregulation of TNF-α has been observed." (PMID 39860614, 2025). "Thus, TAK1 simultaneously governs two major survival pathways, underscoring its potential as a therapeutic target to sensitize cancer cells to TNF-α-induced apoptosis." (PMID 40507823, 2025). "TNF-mediated immune suppression allows cancer cells to escape immune surveillance." (PMID 40547917, 2025). "Form a long-term “training imprint”, significantly enhancing phagocytic ability, cytotoxicity and the secretion capacity of pro-inflammatory cytokines such as IL-1β and TNF-α; In cancer applications, TI inducers represented by BCG vaccines have performed outstandingly." (PMID 41403926, 2025). "Also, a French cohort study compared 255 IBD patients with a history of cancer who were treated with TNF-α antagonists to 30 patients treated with vedolizumab." (PMID 40227584, 2025). "Finally, TNF, a multifunctional cytokine, shows the inflammatory component of cancer progression, with its ability to promote inflammation, cell survival, or apoptosis." (PMID 40227503, 2025). "TNF-α attaches to cell surface receptors, initiating signals inside the cell that may lead to apoptosis in cells with unusual growth patterns, such as cancer cells." (PMID 40006976, 2025). "Conversely, animal model data suggest that TNF may be a cancer immune escape pathway in the context of an inflamed tumour microenvironment and confer resistance to anti-PD-1 therapy." (PMID 40774545, 2025). "The head-to-head studies in this systematic review and meta-analysis did not identify any meaningful difference in the risk of serious infections, malignant neoplasms, or MACEs with JAK inhibitor vs TNF antagonist use across all IMIDs, with low overall incidence." (PMID 40928778, 2025). "CD9 is also shown to associate directly with ADAM17 on the surface of different cell types (cis interactions), including leukocytes and cancer cells, and through this association exerts an inhibitory effect on ADAM17 sheddase activity against its substrates, including TNFα, ICAM-1 or ALCAM." (PMID 38542421, 2024). "Additionally, various factors, including cytokines (interferon, interleukin, and tumor necrosis factor), neurotransmitters (dopamine, GABA, and glutamate), and growth factors, have been proposed to be associated with both SCZ and cancer." (PMID 38592583, 2024). "Furthermore, His-HSP65 (HHSP65), a fusion protein, stimulates the expression of TNF-α and facilitates STEAP1 to enhance TNF-α secretion, effectively inhibiting cancer cell proliferation." (PMID 38339390, 2024). "Furthermore, targeting NF-κB antagonists and upregulating IκB, an NF-κB inhibitor, has been shown to enhance TNF-α-induced cell death in cancer cells." (PMID 39830670, 2024). "IL-1β and TNF-α exhibit a dual effect, demonstrating protective effects during the innate immune response against pathogens and tumors and presenting harmful effects during cancer development." (PMID 38774541, 2024).
cancer (continued). "Nevertheless, in other cancer cell types, it has been shown that diosgenin could revert the TNF effects by increasing the p21 levels." (PMID 39596074, 2024). "The most normal‐like cancer cell cluster Basal_Ca_10 exhibited upregulated TNFα pathway activity." (PMID 38582099, 2024). "In malignant diseases, TNF-α may play a role in cancer therapy and contribute to the host response to tumors, but it may also be involved in cancer progression and spread." (PMID 39795180, 2024). "TNF-α, IL-6, and IL-11 play a critical role in promoting the development and progression of cSCC by creating an inflammatory environment that supports the growth and survival of cancer." (PMID 40013270, 2024). "Despite its multiple functions, TNFα can have conflicting effects on cancer cells." (PMID 38461238, 2024). "deAc-KLF5 upregulates TNF-α in cancer cells to increase FGF9 release by CAFs." (PMID 38781024, 2024). "While the role of TNF in mesenchymal reprogramming is well known, an involvement of Th17 cells in cancer‐associated MMT has not been reported to date." (PMID 38566518, 2024). "This led us to hypothesize that macrophages could induce cancer cell apoptosis through TNF signaling, given the induction of Tnfa expression in macrophages upon BCG treatment." (PMID 39114912, 2024). "For instance, despite previously showing destruction of cancer-supporting blood vessels by TNF-α in cancer patients, intracellular TNFR1 signaling in endothelial cells activates two opposing pathways, one with pro-apoptotic effects, and another NF–κB-mediated pro-survival pathway." (PMID 38698424, 2024). "In addition, administration of EPA to a cancer patient resulted in decreased production of cytokines that promote inflammatory responses (TNF-α, IL-1, and IL-6)." (PMID 39597805, 2024). "To illustrate, administering drugs to cancer patients that focus only on inhibiting IL‐6 could be more effective when TNF‐α is low (group 3) than when it is high (groups 2 and 4)." (PMID 38481033, 2024). "Mechanism of action of various phytochemical compounds in TNF signaling in cancer." (PMID 39104398, 2024). "The function of glucosinolates in cancer prevention is mainly involved in activating the Nrf2 transcription factor, inhibiting tumor necrosis factor-α (TNFα) and interleukin-1β (IL-1β), inducing apoptosis, and modulating other specific inflammatory signaling pathways in cells." (PMID 38672834, 2024). "However, TAMs are unable to recognize cancer as a tissue destined for clearance, suggesting that the TNF signaling axis is reprogrammed in TAMs." (PMID 38698424, 2024). "Additionally, TNF-α induced activation of NF-κB enhances the expression of TBX15 mRNA in cancer cells." (PMID 39286028, 2024). "Understanding the specific interactions between LINC01929 and the TNF pathway may unveil new therapeutic avenues targeting inflammatory and immune pathways in cancer management." (PMID 39586790, 2024). "Concurrently, cancer-related inflammation, often a result of interactions between tumor cells and the immune system, prompts the secretion of various factors that stimulate immune cells to produce TNF-α." (PMID 38396807, 2024). "The pro-inflammatory state induced by chronic HPV infection, characterized by the upregulation of cytokines such as interleukin-6 (IL-6) and tumor necrosis factor-alpha (TNF-α), further promotes oncogenesis by creating a microenvironment conducive to cancer development." (PMID 39338421, 2024). "TNF-α, a proinflammatory cytokine, plays a dual role in cancer biology." (PMID 38406163, 2024). "It is possible that CAR T cells targeting TNFR2 may have a large potential for cancer therapy, in a similar manner as observed for Mb-TNF-α." (PMID 39609700, 2024).